PEX5L (peroxisomal biogenesis factor 5 like)
Description:
Accessory subunit of hyperpolarization-activated cyclic nucleotide-gated (HCN) channels, regulating their cell-surface expression and cyclic nucleotide dependence.
Synonyms: Pex5Rp; TRIP8b; PEX5R; PXR2; PXR2B
Tractability: Antibody: UniProt places it where antibodies can reach, with medium confidence. PROTAC: ubiquitination databases record sites on it; its protein half-life has been measured.
Gene: Protein-coding gene on chromosome 3 (179,794,958 to 180,037,053, reverse strand). Ensembl gene ENSG00000114757.
Subcellular location: Cytoplasm; Membrane
Gene Ontology:
Molecular function: peroxisome targeting sequence binding; small GTPase binding; protein-macromolecule adaptor activity
Biological process: protein import into peroxisome matrix, docking; protein import into peroxisome matrix, translocation
Cellular component: receptor complex; cytosol; peroxisomal membrane; cytoplasm; membrane
Genetic constraint (gnomAD): Loss-of-function variants: 21 observed, 57.28 expected, observed/expected ratio (o/e) 0.37, 90% interval 0.26 to 0.53. The upper end of that interval is the gene's LOEUF score, 0.53, which puts it in group 2 of 6, group 1 being the genes least tolerant of losing a copy. Missense variants: 443 observed, 640.64 expected, observed/expected ratio (o/e) 0.69, 90% interval 0.64 to 0.75. Synonymous variants: 218 observed, 243.28 expected, observed/expected ratio (o/e) 0.9, 90% interval 0.8 to 1.
Homologues: Orthologues: macaque PEX5L (99% identical), chimpanzee PEX5L (99% identical), pig PEX5L (97% identical), dog PEX5L (97% identical), guinea pig PEX5L (97% identical), rabbit PEX5L (97% identical), mouse Pex5l (96% identical), rat Pex5l (96% identical), tropical clawed frog PEX5L (70% identical), zebrafish pex5la (63% identical), zebrafish pex5lb (49% identical), Drosophila melanogaster Pex5 (28% identical), and 1 more. Paralogues in human: PEX5 (38% identical).
Diseases named in the same sentence as PEX5L in open-access papers:
PEX5L is named in the same sentence as 22 diseases in open-access papers, as found by Europe PMC text mining. Sharing a sentence is not in itself a finding about the gene and the disease. The quoted sentences say what the papers report.
gastric cancer (2 papers, 2022 to 2023). A primary or metastatic malignant neoplasm involving the stomach. "Peroxisomal biogenesis factor 5 like (PEX5L) can be an independent prognostic factor for gastric cancer progression." (PMID 36072666, 2022). "PEX5L is correlated with LINC00924 and serves as an independent predictor of peritoneal metastasis in gastric cancer." (PMID 37351109, 2023).
atherosclerosis (1 paper, 2022). A disease characterized by the build-up of fatty material and calcium deposition in the arterial wall resulting in partial or complete occlusion of the arterial lumen. "In addition, cluster 0 expressed Serpinf1, involved in ossification and osteoblast differentiation, Hsd11b1, shown to exacerbate atherosclerosis, Pex5l, expressed in macrophages and Gfra2 in monocytes, as well as cystatin C, associated with coronary artery calcification." (PMID 35163719, 2022).
COVID-19 (1 paper, 2025). A disease caused by infection with severe acute respiratory syndrome coronavirus 2. "Suppressed PEX3, PMP70 and PEX14 immunolabeling in vitro.Suppressed PEX3, PEX11β, PEX5L and PEX14 mRNA levels and decreased PMP70 and PEX14 protein levels in brain tissue from COVID-19 patients versus controls.Suppressed Pex3 mRNA and catalase protein in brains from infected hamsters." (PMID 40949164, 2025).
hearing loss (1 paper, 2012). "The methylation of TP73, the negative expression of cyclin D1, the positive expression of B7-H1, increased expression of platelet-derived growth factor A, underexpression of PEX5L, RAD54B, and PSMAL, and overexpression of CEA are factors associated with hearing loss and VS." (PMID 22567403, 2012).
non-small cell lung carcinoma (1 paper, 2022). A group of at least three distinct histological types of lung cancer, including non-small cell squamous cell carcinoma, adenocarcinoma, and large cell carcinoma. "Genetic variation of PEX5L is closely related to the function of peroxisomes and non-small cell lung cancer survival." (PMID 36090028, 2022).
Obesity (1 paper, 2022). Accumulation of substantial excess body fat. "The study also identified 3 additional genes CLEC7A, MSRB3, and PEX5L that are common among HCL, obesity, and CVD." (PMID 36035865, 2022).
pituitary tumor (1 paper, 2022). A benign or malignant neoplasm affecting the pituitary gland. "PEX5L, also named as TRIP8b, is suggested to function in vesicle transport in mouse pituitary tumor AtT20 cells." (PMID 36090028, 2022).
Vestibular schwannoma (1 paper, 2016). A vestibular schwannoma (also known as acoustic neuroma, acoustic neurinoma, or acoustic neurilemoma) is a benign, usually slow-growing tumor that develops from the VIIIth cranial nerve supplying the inner ear. "PEX5L is expressed in the brain and its underexpression has been found in vestibular schwannomas associated with hearing loss." (PMID 27096627, 2016).
PEX5L also shares sentences with these, for which no sentence is quoted: depression (5 papers); epilepsy (4); absence seizures (3); schizophrenia (2); tumor (2); Anxiety (1); Arrhythmia (1); autism (1); Cognitive impairment (1); colorectal tumor (1); glioblastoma (1); neurodegenerative disease (1); status epilepticus (1); temporal lobe epilepsy (1).